TRAF1 (TNF receptor associated factor 1)
Description:
Adapter molecule that is involved in multiple signaling pathways including the NF-kappa-B and MAPK pathways and thus influences inflammatory and apoptotic responses. Plays a critical role in regulating T-cell activation both through restricting the costimulation-independent activation of NIK in activated T-cells and by promoting the TNFRSF9-induced classical NF-kappa-B pathway (By similarity). Forms a heterotrimer with TRAF2 as part of an E3 ubiquitin-protein ligase complex that mediates ubiquitination of target proteins such as MAP3K14 and gasdermin D/GSDMD. This complex also recruits the antiapoptotic E3 ligases BIRC2 and BIRC3 to TNFRSF1B/TNFR2. Acts downstream of MAVS within the RIG-I/MAVS antiviral pathway to enhance type I interferon signaling. Regulates osteoclastogenesis by preventing ubiquitination and degradation of MLST8, thereby promoting PI3K-AKT signaling and enhancing oxidative phosphorylation in osteoclasts (By similarity). (Microbial infection) Amplifies LMP1-mediated MAP kinase and canonical NF-kappa-B pathway but not non-canonical NF-kappa-B pathway activity.
Synonyms: EBI6; MGC:10353
Tractability: PROTAC: UniProt records ubiquitination sites on it; ubiquitination databases record sites on it; its protein half-life has been measured.
Gene: Protein-coding gene on chromosome 9 (120,902,393 to 120,931,875, reverse strand). Ensembl gene ENSG00000056558.
Subcellular location: Cytoplasm
Subcellular location (Human Protein Atlas): Nucleoplasm
Pathways (Reactome):
Signal Transduction: Regulation of TNFR1 signaling; TNFR1-induced NF-kappa-B signaling pathway
Gene Ontology:
Molecular function: identical protein binding; protein binding; protein-macromolecule adaptor activity; thioesterase binding; tumor necrosis factor receptor binding; ubiquitin protein ligase binding; signaling adaptor activity; zinc ion binding
Biological process: positive regulation of pyroptotic inflammatory response; regulation of extrinsic apoptotic signaling pathway; negative regulation of non-canonical NF-kappaB signal transduction; positive regulation of canonical NF-kappaB signal transduction; protein-containing complex assembly; regulation of canonical NF-kappaB signal transduction; tumor necrosis factor-mediated signaling pathway; regulation of apoptotic process; regulation of signal transduction; signal transduction
Cellular component: cytosol; cytoplasm
Genetic constraint (gnomAD): Loss-of-function variants: 20 observed, 39.02 expected, observed/expected ratio (o/e) 0.51, 90% interval 0.36 to 0.75. The upper end of that interval is the gene's LOEUF score, 0.75, which puts it in group 3 of 6, group 1 being the genes least tolerant of losing a copy. Missense variants: 470 observed, 534.25 expected, observed/expected ratio (o/e) 0.88, 90% interval 0.81 to 0.95. Synonymous variants: 205 observed, 225.14 expected, observed/expected ratio (o/e) 0.91, 90% interval 0.81 to 1.02.
Homologues: Orthologues: chimpanzee TRAF1 (99% identical), macaque TRAF1 (97% identical), rabbit TRAF1 (92% identical), guinea pig TRAF1 (90% identical), pig TRAF1 (89% identical), rat Traf1 (85% identical), mouse Traf1 (84% identical), zebrafish traf1 (45% identical), tropical clawed frog traf1 (44% identical), Caenorhabditis elegans trf-1 (19% identical), Caenorhabditis elegans trf-2 (17% identical). Paralogues in human: TRAF2 (38% identical), TRAF3 (32% identical), TRAF5 (29% identical), TRAF4 (22% identical), TRAF6 (21% identical).
Diseases named in the same sentence as TRAF1 in open-access papers:
TRAF1 is named in the same sentence as 134 diseases in open-access papers, as found by Europe PMC text mining. Sharing a sentence is not in itself a finding about the gene and the disease. The quoted sentences say what the papers report.
rheumatoid arthritis (26 papers, 2010 to 2026). A chronic, systemic autoimmune disorder characterized by inflammation in the synovial membranes and articular surfaces. "Through this network, PIDD1 links indirectly to TRAF1, which, in both whole blood and fetal cortical tissues, is regulated by SNPs associated with rheumatoid arthritis." (PMID 40000109, 2025). "TRAF1 is also regulated by SNPs associated with rheumatoid arthritis in both the fetal cortical tissue and the liver, and a decreased expression of TRAF1 has been associated with increased inflammation." (PMID 40000109, 2025). "Genome-wide association studies have strongly linked a region on chromosome 9 in the TRAF1/C5 locus tagged by several single-nucleotide polymorphisms (SNPs) in linkage disequilibrium, including rs3761847, with an elevated risk of rheumatoid arthritis." (PMID 39062579, 2024). "Numerous studies have established a connection between single-nucleotide polymorphisms (SNPs) in the TRAF1 gene and an increased risk of developing rheumatoid arthritis." (PMID 39062579, 2024). "Others have highlighted a seemingly contradictory effect between innate and adaptive immunity in a TRAF1 polymorphism, which is associated with reduced expression of the protein but paradoxically leads to a gain of function that leads to rheumatoid arthritis." (PMID 39911581, 2024). "Immune-related genes complement component 5 (C5)/TRAF1 located on Chromosome 9q33–34 is identified as a risk factor for rheumatoid arthritis, uveitis in juvenile idiopathic arthritis, multiple autoimmune diseases such as SLE." (PMID 32093731, 2020). "For example, GWAS have identified an association between rheumatoid arthritis and rs3761847, a SNP in an LD block that encompasses two genes that have been implicated in chronic inflammation: TRAF1 and C5." (PMID 27015630, 2016). "The physiological relevance of TRAF1 is supported by observations that polymorphism of genes involved in TNF-receptor signaling such as TRAF1 are associated with rheumatoid arthritis, mortality in sepsis and malignancy." (PMID 24058413, 2013). "TNF receptor-associated factor-1 (TRAF1) and Complement 5 (C5) (TRAF1-C5) lie adjacent to one another on 9q33-34 chromosome and confer susceptibility to diseases such as rheumatoid arthritis (RA) and systemic lupus erythematosus (SLE)." (PMID 23710202, 2013). "PIDD1 was associated with rheumatoid arthritis through the network connecting it with TRAF1." (PMID 40000109, 2025). "Furthermore, genetic studies of rheumatoid arthritis heritability identified single nucleotide polymorphisms (SNPs) in the Chr 9q33.2 region involving PHF19, TRAF1 and C5 as genetic risk factors for rheumatoid arthritis." (PMID 34857028, 2021). "Although TRAF1 has been implicated in the control of rheumatoid arthritis through its regulation on LPS-induced proinflammatory response, whether TRAF1 plays a role in Candida albicans infection is unknown." (PMID 32093731, 2020). "Although a TRAF1 polymorphism has been linked to rheumatoid arthritis, the role of TRAF1 in C. albicans infection was previously unknown." (PMID 32093731, 2020). "Recently an association between a genetic variation in TRAF1/C5 and mortality from sepsis or cancer was found in rheumatoid arthritis (RA)." (PMID 20205706, 2010). "In fact, using TRAF1 knockout mice to determine if and how it affects a complex autoimmune disease, like rheumatoid arthritis, will be complicated by the opposing role that TRAF1 plays in monocytes/macrophages versus T/B lymphocytes." (PMID 39062579, 2024). "Our observation was corroborated by colocalization of a rheumatoid arthritis GWAS signal overlapping the enhancer with a TRAF1 eQTL signal in CD4+ T cells." (PMID 38308274, 2024). "This rheumatoid arthritis GWAS signal colocalized with a TRAF1 eQTL signal in CD4+ T cells and increased risk for rheumatoid arthritis colocalized with increased expression of TRAF1." (PMID 38308274, 2024).
rheumatoid arthritis (continued). "Importantly, TRAF1 polymorphisms have been strongly linked to an increased risk of rheumatoid arthritis (RA)." (PMID 39062579, 2024). "Because of its extensive functionality in pathophysiological processes, TRAF1 has been reported to be involved in various diseases, including ulcerative colitis, rheumatoid arthritis, hepatic steatosis and, especially, various cancers." (PMID 33452764, 2021). "Genome wide association studies have identified an association between SNPs in the 5′ untranslated region of the TRAF1 gene with increased incidence and severity of rheumatoid arthritis and other rheumatic diseases." (PMID 30619326, 2018). "Reduced expression of TRAF1 could explain the association of susceptibility alleles in TRAF1 with rheumatoid arthritis (RA) and other autoimmune diseases." (PMID 28469620, 2017). "This decay pattern was first used empirically in 2007–2008 to fine map the TRAF1 region in rheumatoid arthritis and the IL23R region in psoriasis and has, in an analogous form, subsequently been used in other applications." (PMID 28018425, 2016). "This study investigated the association between single nucleotide polymorphisms (SNPs) in TRAF1/C5 and PTPN22 genes and rheumatoid arthritis (RA) in a Han Chinese population." (PMID 21492465, 2011). "This study investigated five confirmed rheumatoid arthritis (RA) susceptibility genes/loci (HLA-DRB1, PTPN22, STAT4, OLIG3/TNFAIP3 and TRAF1/C5) for association with susceptibility and severity in an inception cohort." (PMID 20353580, 2010). "For instance, the perturbation of an enhancer element upstream of PHF19 that overlaps SNPs in the 95% credible set for a rheumatoid arthritis GWAS signal resulted in immune-related DEGs not reported in K562 cells, including TRAF1." (PMID 38308274, 2024). "However, a rheumatoid arthritis (RA)-associated SNP in the human TRAF1 gene disrupts this restriction on TLR signaling and enhances the production of inflammatory cytokines, providing a compelling explanation for the increased incidence and severity of RA and other inflammatory diseases." (PMID 41446873, 2025). "Crucially, this study did not investigate whether the lower levels of TRAF1 in macrophages directly contribute to rheumatoid arthritis pathogenesis." (PMID 39062579, 2024).
Sepsis (9 papers, 2010 to 2025). Sepsis is defined as life-threatening organ dysfunction caused by a dysregulated host response to infection. "A recent study from our group has shown that the V196A mutation in mouse TRAF1 leads to abrogation of its interaction with cIAP2 in BMDMs and reduced responses to LPS in in vivo models of sepsis and RA." (PMID 41285029, 2025). "Using TRAF1 knockout mice, this study showed that macrophages lacking TRAF1 displayed increased NF-κB activation and cytokine production after TLR stimulation, and that TRAF1-deficient mice were more susceptible to mortality from sepsis." (PMID 39062579, 2024). "Our previous study showed that TRAF1 expression in MSCs is critical for the promotion of macrophage M2 polarization and the alleviation of sepsis." (PMID 36591221, 2022). "TRAF1 is significantly increased in many inflammatory diseases, such as arthritis, enteritis and sepsis." (PMID 34627385, 2021). "Mechanistically, TRAF1 expression in MSCs pretreated with SPIONs was critical for polarization of macrophages to the M2 type and alleviation of sepsis in mice." (PMID 34627385, 2021). "SPION-MSC-expressed TRAF1 was critical for promotion of macrophage polarization and alleviation of sepsis in mice." (PMID 34627385, 2021). "Human variations in TRAF1 correlate with increased incidence of rheumatic disease, increased mortality from sepsis in RA patients, and increased incidence of NHL." (PMID 30619326, 2018). "To further determine whether TRAF1 influences SPION-MSCs to polarize macrophages in the mice with CLP-induced sepsis, we performed experiments as described." (PMID 34627385, 2021). "Gene ontology of these 23 common DEGs showed that apoptotic process (TRAF1, TNFRSF9, ADORA2A, ZBTB16), negative regulation of transcription (SAP30, TSC22D3, ETS2, ZBTB16), and inflammatory response (TNFRSF9, CCL3, ADORA2A) are the main biological processes affected by sepsis treatment." (PMID 30086151, 2018).
breast carcinoma (8 papers, 2004 to 2024). "In human, we first used meta-analysis to establish the association between TRAF1-7 expression and breast cancer survival in patients." (PMID 36944688, 2023). "Moreover, by taking advantage of the published drug response in 44 breast cancer cell lines, we found TRAF1 expression is significant associated with –log10 (TAM GI50) in these breast cancer cell lines." (PMID 24699530, 2014). "B-cell neoplasms and human carcinomas such as melanoma, ovarian cancer, glioblastoma, and breast cancer have been found to implicate TRAF1, TRAF2, TRAF3, and TRAF5." (PMID 37389738, 2023). "To validate the roles of hsa-let-7i and TRAF1 in TAM therapy, we knocked down TRAF1 with siRNA, separately we also over-expressed hsa-let-7i with its mimic in a breast cancer cell line, ZR-75-1." (PMID 24699530, 2014). "Further functional validation confirmed the roles of hsa-let-7i and TRAF1 affecting TAM sensitivity in a breast cancer cell line ZR-75-1, supported the values of our integrative omic analysis approach in the identification of novel biomarkers." (PMID 24699530, 2014). "Further, knock-down TRAF1 and over-expression of hsa-let-7i confirmed the roles of hsa-let-7i and TRAF1 in increasing tamoxifen sensitivity in the ZR-75-1 breast cancer cell line." (PMID 24699530, 2014). "Further testing of these biomarkers in a breast cancer cell line confirmed the roles of hsa-let-7i and TRAF1 in TAM sensitivity." (PMID 24699530, 2014). "Among gene/microRNA that were identified in both ethnic groups, the expression of TRAF1 is also correlated with tamoxifen sensitivity in a collection of 44 breast cancer cell lines." (PMID 24699530, 2014). "In addition, we observed feedback loops concerning nuclear factor kappa B subunit 1 (NFKB1) activation (CHUK, NFKBIA; related to cell survival) in bladder cancer, anti-apoptotic BIRC2/3, and pro-apoptotic TRAF1 factors in breast cancer, respectively." (PMID 28775339, 2017). "The correlation of high TRAF1 expression with high cellular resistance to endoxifen treatment observed in YRI LCLs, and the knocking down of TRAF1 resulting in increased TAM sensitivity in breast cancer cell line both support this hypothesis." (PMID 24699530, 2014). "Surprising specificity of LY294002 in inhibiting IL-6 but not TRAF-1 expression is encouraging as inhibitors with similar properties can be used to reduce invasion of breast cancer cells, more so of ERα-positive cancer cells, by specifically reducing IL-6 expression." (PMID 14970864, 2004). "Similarly, we expanded the breast cancer input layer with the hyaluronan-mediated motility receptor (HMMR) connected to FN1; the TGFBR connected to SNAI1 and SNAI2; the interLeukin 1 receptor type I (IL1R1) and the thyroid hormone receptor beta (THRB) connected to TRAF1 and MYC, respectively." (PMID 28775339, 2017). "Previously, we reported constitutive NF-κB activation in the ERα-negative breast cancer cell line MDA-MB-231, which correlated with increased expression of several NF-κB-inducible genes including IL-6, Mn-SOD, cIAP-2 and TRAF-1." (PMID 14970864, 2004).
autoimmune disease (7 papers, 2011 to 2024). A disorder resulting from loss of function or tissue destruction of an organ or multiple organs, arising from humoral or cellular immune responses of the individual to their own tissue constituents. "SNPS in genes: PADI4 (rs2240340), STAT4 (rs7574865), CD40 (rs4810485), PTPN22 (rs2476601), and TRAF1 (rs3761847) have been described as risk factors for the development of autoimmune diseases, including RA." (PMID 37108746, 2023). "Other studies indicate genetic variants at the TRAF1/C5 locus are associated with autoimmune diseases affecting multiple organs, such as systemic lupus erythematous (SLE), and juvenile idiopathic arthritis." (PMID 21492465, 2011). "To date, no serious attempts have been made to correlate TRAF1 polymorphisms and specific autoantibodies in autoimmune diseases such as RA and SLE." (PMID 23125866, 2012). "Thus, the functional study of TRAF1/C5 with autoimmune disease may provide an insight into the pathogenesis and treatment of these diseases as well as RA." (PMID 21492465, 2011). "Of 223 hypomethylated regions identified, several were in promoters of autoimmune disease GWAS loci (ARID5B, CD69, HDAC9, IL7R, TNIP1 and TRAF1)." (PMID 32231389, 2020).
lymphoma (7 papers, 2014 to 2023). A malignant (clonal) proliferation of B- lymphocytes or T- lymphocytes which involves the lymph nodes, bone marrow and/or extranodal sites. "In line with the evidence of TRAF1 overexpression in HLs and NHLs, TRAF1 deficiency inhibits the spontaneous development of small B cell lymphoma in a transgenic mouse model that expresses the human lymphoma-associated NF-κB2 mutant p80HT specifically in lymphocytes (p80HT tg mice)." (PMID 30294322, 2018). "A previous study showed that TRAF1 is over-expressed in a variety of lymphoma and leukemia cell lines and is a crucial mediator of diverse oncogenic signaling in the development of lymphoid malignancies." (PMID 35911118, 2022). "The gene TRFA1 has an active or passive interaction with many tumor necrosis factor receptor (TNFR), and it has been also shown that TRAF1 plays as an antiapoptotic role in lymphoma cells by activation of NFKB." (PMID 31749827, 2019). "Non-allele-specific ALK RT-qPCR revealed ALK overexpression and 5′ RACE PCR revealed that the patient’s lymphoma expressed a TRAF1-ALK fusion." (PMID 26187744, 2015). "Importantly, crossing the NF-κB2 mutant mice with Traf1−/− mice re-established B cell homeostasis, implicating TRAF1 in the pathogenesis of lymphoma." (PMID 30619326, 2018). "The lymphocytes and lymphoma cells from these transgenic mice express high levels of TRAF1." (PMID 30619326, 2018). "The importance of TRAF1 in lymphoma has also been validated in mouse models." (PMID 30619326, 2018). "Third, p80HT, a lymphoma-associated truncated mutant of p100 lacking parts of the inhibitory domain of the molecule, interacts with the TRAF1 promoter and induces TRAF1 expression." (PMID 24600451, 2014). "Other evidence for the importance of TRAF1 in lymphoma comes from the identification of single nucleotide polymorphisms (SNPs) in the region between TRAF1 and complement factor 5 (TRAF1-C5 locus) that predisposes to lymphoma, although the precise causative SNP has not been identified." (PMID 30619326, 2018). "Treatment of TRAF1-ALK cells with proteasome inhibitors, to block the NF-κB pathway, resulted in p50/p52 downregulation and inhibition of lymphoma growth." (PMID 30619326, 2018). "Notably, TRAF1 protein is consistently elevated in B cell leukemias and lymphomas without evidence of gene amplification." (PMID 30294322, 2018). "Furthermore, treatment of patient ALCL cells expressing the TRAF1-ALK fusion protein with proteasome inhibitors that decrease NF-κB1/2 or a selective ALK inhibitor (CEP28122) results in significant inhibition on lymphoma growth but could not eradicate lymphoma cells." (PMID 30294322, 2018).
anaplastic large cell lymphoma (5 papers, 2015 to 2025). Anaplastic large cell lymphoma (ALCL) is a rare and aggressive peripheral T-cell non-Hodgkin lymphoma, belonging to the group of CD30-positive lymphoproliferative disorders, which affects lymph nodes and extranodal sites. "There is only one fusion of the TRAF1 gene detected in human cancers, the TRAF1-ALK fusion that has been detected in five patients with anaplastic large cell lymphoma (ALCL)." (PMID 30294322, 2018). "Consistently, knockdown of TRAF1 or HOIP resulted in reduced proliferation of a large cell lymphoma cell line." (PMID 30619326, 2018). "However, NGS testing revealed a TRAF1::ALK translocation, which led to a revised diagnosis of stage IV ALK-positive anaplastic large cell lymphoma (ALCL), a curable cancer." (PMID 40161372, 2025).